CAT (catalase)
Diseases named in the same sentence as CAT in open-access papers (continued):
Sharing a sentence is not in itself a finding about the gene and the disease.
infection (continued). "The R20291 φ027 deletant was sensitive to φ027 infection, and contained two unexpected features, a 2.7 kb remnant of the mutagenesis plasmid, and a putative catalase gene adjacent to the deleted prophage was also deleted." (PMID 38966395, 2024). "Data revealed that infection with S. muris caused a significant drop (P < 0.05) in GSH content and SOD and CAT activities, as well as an increase (P < 0.05) in both MDA and NO concentrations compared to the control rats." (PMID 38310115, 2024). "Here, a concomitantly low activity of CAT, APX, and SOD was observed in BSO and DPA treated tissues than WT under infection conditions, which augments susceptibility like U0126-treated tomato plants against B. cinerea infection." (PMID 38592414, 2024). "For example, infection by F. culmorum increases the activity of CAT and POD, as well as the concentration of phenolic compounds in wheat, to resist the pathogen." (PMID 39770747, 2024). "CAT displayed a bimodal expression pattern, reaching a peak at the switching phase (8 dpi) and the late infection phase (21 dpi) in the incompatible interaction." (PMID 39365760, 2024). "As to CAT, the highest activity (p < 0.05) was observed after infection when fish were fed the OPFs/Zn, and the lowest for the fish fed OPFs/C." (PMID 39457892, 2024). "A study conducted on an in vitro model reported that during the first hours after infection, SOD, GST, CAT, and GPx were the main antioxidative enzymes induced in response to the infection." (PMID 38612426, 2024). "Uninfected Morocco plants displayed significantly lower CAT activity, indicating that infection, coupled with GABA treatment, significantly enhances CAT activity." (PMID 39409662, 2024). "We inferred that the host enhanced the levels of CAT and GST activities in response to V. ceranae-caused oxidative stress in the middle stage of the infection process, thereby maintaining homeostasis of the internal environment." (PMID 39628478, 2024). "To confirm the association of H2O2 production and Golgi scattering, we treated Spn D39 WT-infected BEAS-2B cells with the H2O2 degrading enzyme Catalase during infection." (PMID 37592354, 2023). "After 7 days of infection, CAT activity was significantly higher in OEA1 and OEA2 plants than in control plants, whereas it was slightly lower in IEA1 and IEA2 plants than in control plants." (PMID 37107678, 2023). "Typically, pathogen infection causes an imbalance in reactive oxygen species (ROS) and triggers the accumulation of peroxidase (POD), superoxide dismutase (SOD), catalase (CAT), and ascorbate oxidase (APX)." (PMID 37983219, 2023). "Taken together, these results indicated that the SOD and CAT activities exhibited different trends in various insects responding to pathogen infections." (PMID 36671067, 2023). "In susceptible sweetpotato cultivars, the SOD-mediated increase in H2O2 levels 7 days after RKN infection was accompanied by the activation of CAT, which detoxifies H2O2 and reduces total H2O2 levels." (PMID 37371894, 2023). "Numerous studies have reported the critical role of enzymes such as SOD, CAT, APX, PPO, and PAL in reducing the damage caused by pathogen infection to plant cells." (PMID 37361041, 2023). "Both catalase and superoxide dismutase production were lower when CytD was used to block infection of SGP cells, an effect reversed when CytD was used in combination with 0.5% Aq." (PMID 37514180, 2023). "Consistently, this study showed that CAT activity peaked during 5–7 days of infection with C. sojina in GmPR1L-overexpressing soybean plants." (PMID 37107678, 2023). "After 5 days of infection, CAT activity was slightly higher in OEA1 and OEA2 plants than in control plants, whereas it was significantly lower in IEA1 and IEA2 plants than in control plants, which had not reached a significant level." (PMID 37107678, 2023).
infection (continued). "After 3 days of infection, CAT activity was slightly higher in OEA1 and OEA2 plants than in control plants, whereas it was significantly lower in IEA2 plants than in control plants." (PMID 37107678, 2023). "The reduction in CAT activity in inoculated control plants likely contributes to the facilitation of pathogen infection." (PMID 37836249, 2023). "Different from PAL and POD, CAT activity in the phloem varies with varieties for 30 days of infection." (PMID 36840266, 2023). "Meanwhile, SOD and CAT are key antioxidant enzymes involved in protection against immune infection and oxidative stress." (PMID 37569567, 2023). "With the prolonged duration of infection, the activities of CAT and POD exhibited a decline, whereas the concentration of H2O2 showed an accumulation, and the levels of MDA significantly increased." (PMID 38248924, 2023). "In contrast, an increased number of antioxidant-related genes and ROS related genes (RBOHs, peroxidases, L-ascorbate peroxidase, catalase) were upregulated in ‘Eureka’ lemon and ‘Shatian’ pomelo at late infection stage (Supplementary Tabl, e S11)." (PMID 37389294, 2023). "Rather than being necessary for protection within the context of an infection, such high catalase activity enables these strains to exhibit extreme resistance to H2O2 and other oxidative challenges they face in their environmental niche." (PMID 35402311, 2022). "Aphid infestation induced PPO activity, whereas pathogen infection increased the activities of CAT and POD in the plant." (PMID 36845970, 2022). "The CAT activity in the hepatopancreas of M. rosenbergii significantly decreased at 5 days after spiroplasma MR-1008 infection and showed a recovery at 15 days; however, the mRNA expression level was up-regulated and peaked at 12 days." (PMID 36009210, 2022). "The results of this study dealt with the estimation of the activity of antioxidant defense enzymes and indicated that infection with Alternaria fungus caused a significant increase in enzymes (SOD, CAT, POD and PPO) compared to healthy plants." (PMID 36030517, 2022). "On the other side, following infection with A. hydrophila, significant upregulations of both CAT and GPx were measured in the tilapias supplied with a moringa-free diet (0% moringa) (p < 0.05)." (PMID 35812877, 2022). "In our study, the activities of SOD was significantly increased in the intestine of the M. japonicus under DIV1 infection, while the activities of CAT was significantly decreased." (PMID 36189245, 2022). "In vivo analysis indicated that SiNPs decreased the degree of decay around the wounds and decreased the accumulation of H2O2 after long-term pathogenic infection through potentiating the activities of antioxidant enzymes such as SOD, APX, PPO, and CAT." (PMID 35564127, 2022). "Next, we evaluated the levels of catalase production across the established infection samples by measuring a zone of inhibition in the presence of reactive oxygen species (e.g., H2O2) via phenotypic profiling." (PMID 35862772, 2022). "Feeding moringa having a diet to mono-sex Nile tilapia modified the relative expression levels of some antioxidant genes such as CAT and GPx under normal health conditions and the infection with A. hydrophila after 24 and 48 h of exposure." (PMID 35812877, 2022). "For instance, C. neoformans modulates the production of catalase and melanin during infection with bursts of production upon initial interactions with macrophages but dissipates levels of these two well-characterized virulence factors over time." (PMID 35862772, 2022). "At 12-h post-bacterial challenge, hepatic CAT activity decreased while the content of MDA increased (P < 0.05) relative to pre-infection levels." (PMID 34973140, 2022). "Other than higher ROS/RNS enzyme expression, host catalase (CAT) gene expression is also induced by infection in the presence of SS." (PMID 35573801, 2022).
infection (continued). "Our data presented the upregulation in gene expression levels of PAL and SOD in both cultivars to pathogen infection, but partially in the levels of CAT and APX in the resistant cultivar." (PMID 35205903, 2022). "Cluster II, including genes downregulated after infection, dominated (57.14%); among this cluster are genes encoding 3 SOD, 1 CAT, 12 peroxidase, 2 glutaredoxin, 1 peroxiredoxin, and 5 thioredoxin." (PMID 35616396, 2022). "PAL activity and CAT activity first decreased but then increased during the process of pathogen infection." (PMID 35774503, 2022). "In this study, the activity of enzymes involved in ROS scavenging, including SOD, POD, PPO and CAT, was notably induced during infection, which is in line with the expression patterns of the related genes." (PMID 36008749, 2022). "The current study showed that the infection with H. pylori significantly decreased catalase activity (p< 0.001)." (PMID 36139826, 2022). "CAT2 overexpression led to a higher CAT enzyme activity and enhanced resistance to oxidative stress and pathogen infection in transgenic N. benthamiana plants." (PMID 36311133, 2022). "After 36 h infection with B. cinerea, the CAT activity of transgenic Arabidopsis increased, while the CAT content of MnASI1 transgenic Arabidopsis was significantly higher than that of empty vector transgenic Arabidopsis." (PMID 36362160, 2022). "For C. neoformans immediate infection samples, only one catalase was detected in the proteome (i.e., CNAG_04891) with a significantly lower abundance than the fungal established infection samples." (PMID 35862772, 2022). "On the other hand, the accumulation of CAT showed a positive correlation with the TaTrx genes showed downregulation during the span of infection." (PMID 35401694, 2022). "As the infection with H. pylori causes a decrease in catalase activity, the effect of PEAME on catalase activity was investigated." (PMID 36139826, 2022). "It has been observed that the preventive inoculation of a beneficial microorganism reduces the incidence and severity of an infection by some phytopathogens, increasing total protein and CAT activity." (PMID 35406912, 2022). "While the extracellular CAT KatG2 in the rice blast fungus Magnaporthe oryzae exhibits a moderate contribution to infection during the early stages." (PMID 37676381, 2021). "The results showed that SOD and CAT increased during the early stage of infection but decreased with the extension of infection time." (PMID 34827209, 2021). "Females infected with L. mexicana-CAT, showed only slightly lower parasite burden during the early stages of infections (χ2 = 1.193, df = 1, p = 0.379 and χ2 = 4.559, df = 1, p = 0.066 on day 2 and 5 PBM, respectively)." (PMID 33724149, 2021). "The activities of SOD and POD were induced after leaves were infected, and then decreased, with a gradual decrease in CAT during the infection period." (PMID 35082814, 2021). "We labeled peroxisomes in infected cells by immunostaining for catalase and analyzed the dependence of peroxisome size on the stage of infection." (PMID 33380421, 2021). "It was also showed that treatment with P. indica contributes to modulate the enzymatic activity of superoxide dismutase, catalase, phenylalanine ammonia-lyase and peroxidase, in the course of infection." (PMID 34578118, 2021). "Two other genes were targeted as indicators for oxidative stress inside G. mellonella gut along the infection process: the superoxide dismutase sodA and a catalase gene." (PMID 34374318, 2021). "Initial vaccination strategies were based on antigens derived from secreted proteins like urease, VacA, CagA, and catalase, that reduced bacterial load upon infection with H. pylori." (PMID 34203937, 2021). "Prior to infection, the CAT activity in the transformants was 0.97 ± 0.01-fold higher than that in the WT Pdpap." (PMID 34490017, 2021).
infection (continued). "The results showed that SOD and CAT activities increased after coral was infected by ciliates but decreased with the extension of infection time." (PMID 34827209, 2021). "Hallmarks of cell death and inflammation, including cleaved caspase-1 and −3, gasdermin-D, neutrophil elastase, catalase, complement C3, and myeloperoxidase were validated in lung tissues on day 6 after infection via immunoblot." (PMID 34319784, 2021). "Upon Lxx infection, the genes encoding POD, SOD and CAT were up-regulated, indicating plant’s defense to maintain photosynthesis to some extent." (PMID 33529190, 2021). "Expectedly, the transmission efficiency of L. mexicana-CAT was dramatically lower than that of the wild type, emphasizing the need of metacyclic promastigotes for mammalian host infection." (PMID 33724149, 2021). "After infection by M. bicuspidata, the CAT gene expression level in the hemolymph tissue of E. sinensis increased to 2.4 times higher than that of the control group." (PMID 33868309, 2021). "To investigate this in detail, we established a L. mexicana line that expressed catalase during differentiation, and explored the role of the enzyme in vitro and in vivo, both in sandflies and mouse models of infection." (PMID 33724149, 2021). "After 36 hours of infection by B. cinerea, the CAT activity of MnChi18 transgenic Arabidopsis was significantly higher than that of the empty vector transgenic Arabidopsis." (PMID 35052438, 2021). "Next, we tested the ability of L. mexicana-CAT to establish infection in mouse bone marrow-derived macrophages (BMMɸ)." (PMID 33724149, 2021). "While dps was up-regulated (2.60-fold change), the superoxide dismutase sodA had a level of expression (0.99 -fold change) similar to the early infection stage, and finally the catalase was down-regulated (0.77 -fold change)." (PMID 34374318, 2021). "Certain Scedosporium proteins such as cytosolic catalase have been studied as markers of infection as have various metabolites and siderophores of these fungi, but currently these markers are limited to research laboratories." (PMID 33406673, 2021). "In apricots, the infection produced a decrease in CAT, POX, and SOD activities and a strong increase in PPO." (PMID 34357359, 2021). "After infection, the activity of CAT in plasma and most intestinal segments decreased, while the intervention of ZnO increased the activity of CAT in the intestine." (PMID 34257799, 2021). "The levels of the antioxidant enzymes (SOD, GSHPx, and CAT) were significantly reduced in G3 compared to those in G1 on the 7th and 14th day of infection." (PMID 35071376, 2021). "It has long been recognized that C. glabrata's intrinsic resistance to oxidative stress occurs through the high expression of detoxifying enzymes (catalase and superoxide dismutase) during infection." (PMID 33680221, 2021). "Concentrations of glutathione (GSH), malondialdehyde (MDA), nitric oxide (NO), superoxide dismutase (SOD), and catalase (CAT) were analyzed in the plasma, brain, and bursa on days 0, 3, and 7 post-infection (pi) using the biochemical method." (PMID 34840466, 2021). "Both Spm and Spd induced the activities of catalase, ascorbate peroxidase, and guaiacol peroxidase after treatment but also after infection with B. cinerea." (PMID 33562549, 2021). "The catalase mutant ∆KatG2 from Fusarium graminearum, exclusively located on the cell wall of invading hyphal cells, reduced the virulence in wheat spike infection." (PMID 37676381, 2021). "We demonstrated that catalase-expressing L. mexicana are defective both in vitro and in vivo (in sandflies and mice infection models), further supporting our premise that catalase presence is not compatible with the dixenous life cycle of Leishmania." (PMID 33724149, 2021). "Morphological analysis of the infections 9 days PBM (500 promastigotes per strain) revealed that development of L. mexicana-CAT was considerably impaired, compared to that of L. mexicana-mCHERRY." (PMID 33724149, 2021).
infection (continued). "We concluded that parasites, expressing catalase, retained the ability to produce heavy infection in the natural vector L. longipalpis with colonization of the stomodeal valve and production of metacyclic parasites." (PMID 33724149, 2021). "Of note, the importance of the S. aureus catalase gene has previously been shown in vitro during intracellular infection in murine macrophages or in vivo through intraperitoneal injection with a ΔkatA clinical bovine strain." (PMID 34126772, 2021). "Higher levels of MDA, catalase, carotenoids, anthocyanins, phenolic compounds, and lignin were detected in chitosan-elicited plants following infection." (PMID 33580134, 2021). "After infection, CAT activity was significantly higher in all the PA-treated plants compared to the controls, although a rather similar pattern was also observed in uninfected controls." (PMID 33562549, 2021). "In this study, two antioxidant enzymes (SOD and CAT) were used to judge the stress response in Goniopora columna after infection, and KCl and H2O2 were used to evaluate the therapeutic effect." (PMID 34827209, 2021). "For example, it is reported that pathogen infection-induced ROS overaccumulation results in dysfunction of catalase through direct oxidative modification." (PMID 34177987, 2021). "In our greenhouse study, we observed that the activity of SOD, GPX, PAL, and CAT enzymes was even more increased in plants in which infection with S. vesicarium was preceded by treatment with P. indica." (PMID 34578118, 2021). "The foliar application of alginates induced SAR by stimulating the accumulation of H2O2 in response to pathogen infection and by reducing the activity of catalase (CAT) involved in the scavenging of H2O2." (PMID 33504049, 2021). "It was demonstrated that catalase is involved in bacterial protection from oxidants and oxidative stress, suggesting its heterogeneous ways of action during infection." (PMID 33375694, 2020). "In the case of susceptible genotypes, comparatively higher decrease in CAT activity and elevated H2O2 level cause oxidative burst in living cells adjoining the infection site and finally cell death to benefit the necrotrophic phase of S. sclerotiorum." (PMID 33121098, 2020). "A core set of effectors was prominently induced (FPKM > 100) during infection independently of the host genotype (e.g., a catalase, an expansin-like gene, an endoglucanase, and several pioneer genes)." (PMID 33096989, 2020). "In a previous short-term evaluation, APX and CAT transcriptional levels in both A. chinensis and A. arguta were found to be little affected during the first 5 days after Psa and Pfm infection, whereas SOD overexpression in A. chinensis was observed 5 dpi." (PMID 32793252, 2020). "The enzymatic response of S. litura to combined matrine and B. brongniartii treatment displayed a reduction in GSTs, SOD, POD, and CAT after 3 days of infection." (PMID 33224038, 2020). "In vivo, catalase expression also impeded the ability of T. brucei to establish infection in the midgut of the tsetse fly." (PMID 32520929, 2020). "Agrobacterium infection alone induced only a slight increase in CAT activity at 48 h post infection." (PMID 33193244, 2020). "Pathogen infection significantly increased the CAT activities of E+ plants at all soil water regimes." (PMID 33276437, 2020). "Hemoglobin’s catalase and nitric oxide dioxygenase activities are important in protection against host immune responses to infection." (PMID 32429519, 2020). "As a result of the duplication of katA that had occurred during infection, this reisolate displayed higher catalase activity and was less sensitive to oxidative stress induced by paraquat." (PMID 32843556, 2020). "Plants treated with GABA showed reduced H2O2 accumulation after infection due to increased activity of catalase and guaiacol peroxidase." (PMID 33255543, 2020).